PNPLA3 (patatin like domain 3, 1-acylglycerol-3-phosphate O-acyltransferase )
Diseases named in the same sentence as PNPLA3 in open-access papers (continued):
Sharing a sentence is not in itself a finding about the gene and the disease.
liver disease (continued). "In our study, we evaluate how the PNPLA3 mutation plays a part in the progression of liver disease in prediabetes." (PMID 33520810, 2020). "Carriage of PNPLA3 G∗ allele was associated with a trend of progressively more severe liver disease, from mild fibrosis to significant fibrosis, cirrhosis, and HCC (p = 0.007)." (PMID 32382265, 2020). "Single nucleotide polymorphisms (SNPs) associated with obesity, in particular in the Patatin-like Phospholipase 3 (PNPLA3) gene, have been associated with liver disease and cirrhosis in GWAS." (PMID 30978214, 2019). "Just recently, a genetic variant of the patatin‐like phospholipase domain containing 3 (PNPLA3) gene has been linked to increased risks of hepatic decompensation and mortality in patients who had already developed portal hypertension." (PMID 31062417, 2019). "Multiple genetic studies have since validated the association of PNPLA3(148M) with a broad spectrum of liver diseases ranging from ALD and NAFLD, non-alcoholic steatohepatitis (NASH), fibrosis, cirrhosis, and hepatocellular carcinoma (HCC)." (PMID 31921875, 2019). "Clinically, aside from causing intrahepatic triglyceride accumulation, the PNPLA3 I148M variant has also been shown to increase the risk of progressive liver disease." (PMID 30355853, 2018). "The results obtained in this study support that the FLD-related PNPLA3 rs738409 genetic variant is associated with liver disease progression in HIV/HCV-coinfected patients." (PMID 27973562, 2016). "A more comprehensive approach to this problem is to test the influence of PNPLA3 rs738409 G allele on the progression of liver disease." (PMID 27973562, 2016). "The mechanisms linking the I148M PNPLA3 variant with liver disease progression and hepatocellular carcinoma development have recently been reviewed by our group." (PMID 26273621, 2015). "Although the mechanism underlying the progression to liver disease remains an area of active research, PNPLA3 has a triglyceride and retinyl-palmitate esterase activity." (PMID 26273621, 2015). "Effect of I148M PNPLA3 variant on clinical presentation of HCC according to the etiology of liver disease (ALD & NAFLD vs. other etiologies)." (PMID 24155878, 2013). "A variant in PNPLA3, an enzyme that promotes transfer of long-chain polyunsaturated fatty acids (LCPUFAs) from triglycerides to phospholipids in lipid droplets (LDs), is a major risk factor for steatotic liver disease." (PMID 41278711, 2025). "This association suggests that routine liver MRI of SLD patients could be used to identify a population that might benefit from PNPLA3 I148M screening, hence identifying individuals at higher risk of developing more severe liver disease phenotypes." (PMID 40478199, 2025). "Finally, the present report contributes to a growing body of literature emphasizing the multisystemic impact of PNPLA3 variants, underlining the importance of considering liver disease surveillance in syndromic patients." (PMID 41157259, 2025). "For instance, the PNPLA3 gene in Hispanics may accelerate liver inflammation from steatotic liver disease, increasing liver cancer risk." (PMID 40227653, 2025). "Thus, the loss-of-function PNPLA3 rs738409 variant is associated with increased intrahepatic triglyceride deposition, leading to an inflammatory process, progressive liver disease, and the development of HCC." (PMID 40725464, 2025). "In addition to lipid droplet accumulation, PNPLA3-I148M expression caused significant proteomic and transcriptomic changes that resembled all stages of liver disease." (PMID 38657050, 2024). "PNPLA3-I148M causes altered Golgi morphology and drives changes reminiscent of liver disease." (PMID 38657050, 2024). "However, these patients showed a very high prevalence of PNPLA3 G allele which probably represented the main pathophysiological cause of their severe liver disease." (PMID 35327522, 2022).
liver disease (continued). "In addition, in a recent study on 471 NAFLD patients prospectively enrolled and followed for a median of 5.4 years, a twofold increased risk of severe liver disease among carriers of the C > G allele of PNPLA3 was reported." (PMID 36166317, 2022). "The PNPLA3 I148M variant status may help refine the risk stratification for liver disease in persons with excessive drinking and obesity who may need early preventive measures." (PMID 36190732, 2022). "Given the influence of PNPLA3 in the progression of liver disease and the frequency of this genetic predisposition among Mexican-origin adults, the current study aimed to identify appropriate strategies to communicate PNPLA3 risk status to Mexican-origin men as a means to promote NAFLD prevention." (PMID 36684893, 2022). "In this cohort study of 414 209 participants in the UK Biobank study, the PNPLA3 I148M variant had synergistic associations with the risk of cirrhosis, hepatocellular carcinoma, and liver disease–related mortality along with excessive alcohol intake and obesity." (PMID 36190732, 2022). "While PNPLA3 has been studied in various settings, the value of both SNPs has so far not been addressed in a real-world cohort of subjects referred for a diagnostic work-up of liver disease." (PMID 33804385, 2021). "Specifically, we confirm the strong association between PNPLA3 and liver disease severity." (PMID 33804385, 2021). "PNPLA3 variant predominantly increases the triglyceride content, and its effect increases with the presence of metabolic comorbidities or additional causes of liver disease." (PMID 33804385, 2021). "However, 71% of them were carriers of the PNPLA3 G allele, which modulates liver disease severity by favoring disease progression." (PMID 31505904, 2019). "Our finding may explain, at least in part, the more aggressive course of liver disease observed in patients carrying PNPLA3 variant, as patients with portal fibrogenesis are more prone to develop progressive liver disease and liver-related mortality." (PMID 29150621, 2017). "Moreover, as a validation of this finding, we detected a higher frequency of PNPLA3 rs738409 G allele carriers in a group of HIV-infected individuals who had reached end-stage of liver disease due to HCV infection." (PMID 27973562, 2016). "Such potential examples of genotypes that are associated with a dissociation between liver disease and metabolic syndrome are patatin-like phospholipase domain-containing protein-3 (PNPLA3) (I148M) and transmembrane 6 superfamily member 2 protein (TM6SF2) (E167K) genotypes." (PMID 26978356, 2016). "The association of PNPLA3 148M with younger age, shorter history of cirrhosis, and less advanced liver disease at HCC diagnosis in ALD&NAFLD is therefore in line with direct carcinogenic activity of PNPLA3 148M, so that 148M homozygotes develop HCC before the other complications of cirrhosis." (PMID 24155878, 2013). "Aim of this study was to evaluate whether the I148M PNPLA3 polymorphism influences serum adiponectin in liver diseases and healthy controls." (PMID 22898488, 2012). "As the PNPLA3 variant allele is the most frequent risk modifier among cirrhotic patients, we analysed a larger group of cirrhotic patients to establish the impact of concomitant carriage of both variants on the severity of liver disease in the liver transplant settings." (PMID 41004464, 2025). "Indeed, PNPLA3 GG and CG accounted for most patients in our cohort (38.0% and 36.1%, respectively), reflecting the enrichment of the risk genotypes in individuals with progressive liver disease." (PMID 40002828, 2025). "Findings of this study suggest that genotyping for the PNPLA3 I148M variant may be useful in refining the risk stratification of persons with obesity and excessive drinking who are at risk for advanced liver disease progression and may be candidates for early preventive measures." (PMID 36190732, 2022).
liver disease (continued). "Our data confirm the central role of PNPLA3 across the whole spectrum ofhile SERPINA1 risk alleles may be particularly relevant in the development of advanced fibrotic stages or for the decompensation of liver disease." (PMID 33804385, 2021). "Even though it has been studied intensively in different settings within the last 6 years, the influence of a genetic polymorphism in the patatin-like phospholipase domain-containing 3 (PNPLA3)-gene (rs738409) on liver disease progression in HIV/HCV coinfected patients remains unclear." (PMID 26599080, 2015). "Collectively, our study expands the current understanding of PNPLA3-148M function by revealing its macrophage-specific impact on liver disease pathogenesis." (PMID 41564367, 2026). "Over the past 15 years, PNPLA3 has emerged as one of the most influential genetic determinants of liver disease." (PMID 41516346, 2026). "Genetic variation in PNPLA3 influences liver fat accumulation and hepatocellular injury in various liver diseases." (PMID 41516346, 2026). "The PNPLA3 p.I148M allele is one of the strongest genetic risk factors for MASLD and for other liver diseases." (PMID 41487453, 2026). "In our opinion, their findings regarding the role of both genes in the course of liver disease are compatible with our results and can explain the surprisingly younger age of the PNPLA3 CC carriers in the whole cohort of cirrhotic patients." (PMID 41004464, 2025). "Like the PNPLA3 variant, TM6SF2 rs58542926 contributes to the progressive liver disease in patients with MASLD, initiating from simple steatosis to progressive fibrosis and cirrhosis." (PMID 40725464, 2025). "One of the most extensively studied genetic contributors to liver disease is the patatin-like phospholipase domain-containing 3 (PNPLA3) gene." (PMID 40831836, 2025). "Preclinical studies showed that these new drugs are able to interfere with PNPLA3 synthesis by silencing the corresponding gene, thus reducing liver disease." (PMID 39940335, 2025). "This study evaluated the distribution of PNPLA3 rs738409, TM6SF2 rs58542926, and HSD17B13 rs6834314 and overall survival of HCC patients with metabolic dysfunction-associated steatotic liver disease (MASLD-HCC) and viral-related HCC (VIRAL-HCC)." (PMID 40725464, 2025). "Indeed, patatin-like phospholipase domain-containing protein 3 (PNPLA3) genetic polymorphisms are associated with increased risk of liver disease progression, cirrhosis, and HCC, and emerging data suggest that PNPLA3 may play a role in differential response to GLP-1 based regimens in MASH." (PMID 40590228, 2025). "This phenomenon is known to involve both PNPLA3 and TM6SF2 and explains the discordant effects of some genetic variants on liver disease versus coronary artery disease." (PMID 40297446, 2025). "In this context, rs738409 (C > G), a single nucleotide polymorphism (SNP) in the Patatin-like phospholipase domain containing 3 (PNPLA3) gene, has been strongly associated with the full spectrum of liver disease." (PMID 40806538, 2025). "All in all, the discovery of PNPLA3 variation as a main determinant of liver disease and the research field it has opened has brought about several innovations in liver research." (PMID 40747912, 2025). "Although significant associations between the PNPLA3 GG carriage and MASLD have been documented in several studies, studies regarding the association between the SIRT5 rs12216101 variant and advanced liver disease in patients with MASLD are scarce." (PMID 39596570, 2024). "The effect of MLXIPL Gln241His on liver disease was most pronounced among those at the highest risk of SLD, namely those with obesity, T2D mellitus, and carriers of PNPLA3 I148M." (PMID 38668731, 2024). "We found that high alcohol intake (>14 units per week), obesity (BMI > 30 kg m−2) and T2D also amplified the effect of PNPLA3 p.Ile148Met on hepatocellular carcinoma (HCC) and all-cause liver disease." (PMID 38632349, 2024).
liver disease (continued). "All in all, these results demonstrate an interaction between female sex and the PNPLA3 p.I148M variant in determining MASLD, contributing to sex‐specific differences in the susceptibility to the most common cause of liver disease." (PMID 38224202, 2024). "A good example is patatin-like phospholipase domain-containing protein 3 (PNPLA3) genetic testing for NAFLD susceptibility and hereditary hepatic disease, which is used clinically in Europe and the US." (PMID 36809439, 2023). "The PNPLA3 I148M variant status significantly differentiated the risk of cirrhosis, HCC, and liver disease–related mortality in persons with excessive drinking and obesity." (PMID 36190732, 2022). "For example, one report highlighted asthma as a possible adverse event when using PNPLA3 inhibitors to manage liver diseases." (PMID 36294997, 2022). "We collected clinical, demographic, and biochemical data, and we performed a genotyping analysis for common variants previously associated with liver disease risk (HSD17B13 rs72613567:TA and PNPLA3 rs738409)." (PMID 36233142, 2022). "It provides a unique opportunity to prospectively and longitudinally investigate the roles of the PNPLA3 I148M variant, obesity, and alcohol intake in the risk of cirrhosis, HCC, and liver disease–related mortality." (PMID 36190732, 2022). "We found similar synergistic associations between the PNPLA3 I148M variant, obesity, and alcohol intake in the risk of progression to HCC and liver disease–related mortality." (PMID 36190732, 2022). "Synergistic interactions between the PNPLA3 I148M variant, obesity, and alcohol intake were associated with the risk of cirrhosis, HCC, and liver disease–related mortality." (PMID 36190732, 2022). "Results of this study suggest that the PNPLA3 I148M variant, obesity, and alcohol intake interact synergistically and are associated with increased risk for cirrhosis, HCC, and liver disease–related death." (PMID 36190732, 2022). "In this study, we aimed to investigate the joint associations of the PNPLA3 I148M variant, alcohol intake, and obesity with the risk of cirrhosis, HCC, and liver disease–related mortality." (PMID 36190732, 2022). "The role of PNPLA3 (patatin-like phospholipase domain containing protein 3) in the pathogenesis and disease progression of several liver diseases, including PSC has also been studied." (PMID 36454904, 2022). "This study found synergistic associations of the PNPLA3 I148M variant, excessive alcohol intake, and obesity with increased risk of cirrhosis, HCC, and liver disease–related death in the general population." (PMID 36190732, 2022). "Genome‐wide interaction study identified 9 ALT and 12 AST independent associations significantly modified by body mass index (BMI), including several previously reported potential liver disease therapeutic targets, for example, PNPLA3, HSD17B13, and MARC1." (PMID 34184762, 2021). "Further studies are needed to elucidate the genetic role of PNPLA3 in the severity of liver disease and its relationship with post-SVR evolution." (PMID 34833371, 2021). "Strengths of the current study include our focus on MO adults who are underrepresented in the liver disease literature and have among the highest rates of obesity, NAFLD, and prevalence of the PNPLA3 variant." (PMID 34280991, 2021). "Since its identification, the PNPLA3-I148M human variant has broadly been associated with progression of NAFLD and other liver diseases, including HCC." (PMID 33672787, 2021). "The results showed that patients with PNPLA3 I148M genotype were more likely to have liver fat and fibrosis, and have a higher mortality rate from liver disease." (PMID 34476007, 2021). "PNPLA3 I148M is closely related to liver disease and its complications, and according to the current research, it is mainly related to the accumulation of lipids in the liver." (PMID 34476007, 2021).
liver disease (continued). "A genetic mutation of PNPLA3, the I148M polymorphism, has been strongly correlated with a higher risk of developing fibrosis in NAFLD and other liver diseases." (PMID 33218077, 2020). "We replicated previous GWAS results, reporting a significant association of TSLP and RORA gene variants with asthma and GCKR, PNPLA3, TRIB1 and TM6SF2 gene variants with the risk of developing liver diseases, notably NAFLD/NASH." (PMID 30978214, 2019). "The steatogenic alleles in PNPLA3, TM6SF2, GCKR and MBOAT7 all associated with increased risk of ICD‐defined ‘other diseases of liver’ (K76), which includes NAFLD (n = 408 455, P = 0.0075–2 × 10−12)." (PMID 29280273, 2018). "The genetic factors that play a role in late-stage liver disease remain controversial, although several studies have shown that variants in MICA, DEPDC5, HCP5 and PNPLA3 affect HCC development." (PMID 28928439, 2017). "PNPLA3 SNPs were associated with increased liver fibrosis progression in HCV-monoinfection, HIV-monoinfection and other etiologies of liver disease." (PMID 26599080, 2015). "PNPLA3 148M is over-represented in ALD&NAFLD HCC patients, and is associated with occurrence at a less advanced stage of liver disease in ALD&NAFLD." (PMID 24155878, 2013). "The weaker association between PNPLA3 genotype and carotid atherosclerosis in Northern Italian, compared to Sicilian patients, could be expression of the lower prevalence of PNPLA3 GG genotype, metabolic dysfunctions and severity of liver disease observed in the validation cohort." (PMID 24069270, 2013). "Leave-one-out analysis indicated that the association between PNPLA3 inhibition and liver diseases was unlikely to be significantly influenced by any single SNP." (PMID 40881642, 2025). "PNPLA3 rs738409 is a major genetic determinant of steatotic liver disease and its severity." (PMID 41004464, 2025). "This deviation is likely biologically driven rather than technical, as the PNPLA3 148M (G) allele is a well-established and potent risk factor for steatotic liver disease." (PMID 41244049, 2025). "Furthermore, the effect of PNPLA3 on fibrosis severity among patients with different liver diseases has been established, with the presence of the SNP leading to the activation of HSCs." (PMID 39394864, 2025). "Several modalities targeting PNPLA3 for silencing are already under clinical development, which may enable the first precision medicine approach in hepatology tackling the roots of liver disease." (PMID 40747912, 2025). "This is consistent with a model where the accumulation of the enzymatically inactive p.I148M inhibits PNPLA2, leading to liver disease, whereas higher levels of wild‐type enzymatically active PNPLA3 may even be protective." (PMID 40747912, 2025). "Silymarin/silybin regulates a significant number of these lipid metabolic genes, including iPLA2/PLA2G6, ATGL/PNPLA2, PLD1, LPIN2, and by trend PNPLA3 (which is a major genetic risk factor for MAFLD 131) and HSD17B13, counteracting the observed dysregulation in liver diseases." (PMID 39897559, 2025). "–78 In addition to revealing the importance of lipid droplet turnover in MASLD, the linkage of PNPLA3-rs738409-G to both MASLD and alcohol-associated liver disease has shed light on the common pathways of liver injury seen in these 2 distinct types of chronic liver disease." (PMID 39774697, 2025). "The PNPLA3 I148M variant showed synergistic interplay with heavy alcohol intake and obesity and was associated with increased risk of developing cirrhosis, HCC, and liver disease–related death in a middle-aged population." (PMID 36190732, 2022). "The G/G genotype (I148M) of the PNPLA3 gene was associated with a higher rate of progression to severe liver disease in patients with NAFLD and particularly in patients without advanced fibrosis at diagnosis." (PMID 36166317, 2022).